CCNB1 (cyclin B1)
Diseases named in the same sentence as CCNB1 in open-access papers (continued):
Sharing a sentence is not in itself a finding about the gene and the disease.
prostate carcinoma (62 papers, 2005 to 2025). A carcinoma that arises from epithelial cells of the prostate gland. "Further analysis of the mutation frequency of the CCNB1 gene across various cancer types showed that prostate cancer (4.05%), ovarian epithelial tumor (3.94%), ACC (3.3%), endometrial cancer (3.24%), and bladder cancer (2.19%) had the highest frequencies." (PMID 38581717, 2024). "Studies have also confirmed that the treatment of human prostate cancer cells with 2-methoxyestradiol or docetaxel causes cyclin B1 protein accumulation and an increase in cyclin B1 kinase activity, followed by induction of apoptotic cell death." (PMID 37759511, 2023). "Elevated levels of cyclin B1 have been associated with polyploid cell uptake and shown to be a potential marker for diagnosing prostate cancer." (PMID 37107559, 2023). "Triol caused reduction of Akt1, cyclin E2, cyclin B1, phospho-c-Myc Thr58/Ser62, c-Myc, and phospho-Akt Ser473 in all three prostate cancer cell lines." (PMID 23785446, 2013). "Furthermore, in prostate cancer, CCNB1 expression was linked to poor prognosis, with knockdown of CCNB1 inhibiting cell proliferation and metastasis." (PMID 40682115, 2025). "In our MWA screening using 48 antibodies against proteins involved in Akt signaling and cell cycle regulation, we observed that triol caused reduction of Akt1, Akt2, cyclin E2, cyclin B1, phospho-c-Myc Thr58/Ser62, c-Myc, and phospho-Akt Ser473 in all three prostate cancer cell lines." (PMID 23785446, 2013). "To find the effects of green tea extract on PC3 prostate cancer cells through inhibition of cell proliferation, we investigate the expression of cyclin B1 and CDK1 (that are important to mitosis progress) utilizing the western blot technique." (PMID 40336533, 2025). "Evidence suggests that aberrant CCNB1 expression is correlated with unfavorable survival outcomes in various cancers, including ovarian carcinoma, prostate cancer, and lung adenocarcinoma." (PMID 40682115, 2025). "Similar to the present results, cyclin B1 overexpression has been reported to sensitize prostate cancer cells to PTX." (PMID 39710372, 2024). "The mutation frequency of the CCNB1 gene was comparatively high in prostate cancer, ovarian epithelial tumor, ACC, endometrial cancer, and bladder cancer, highlighting the need to investigate the link between CCNB1 mutations and urogenital system cancers." (PMID 38581717, 2024). "Recently, it has been shown that HN1 silencing sensitizes Prostate cancer cells to chemotherapeutic agents such as 2-Methoxyestradiol and Docetaxel via Cyclin B1 regulation." (PMID 36829467, 2023). "A positive correlation between cyclin B1 protein and chemotherapy-induced apoptosis in prostate cancer cells has been demonstrated." (PMID 37759511, 2023). "Galiellalactone increases ATM/ATR, p-Chk1 (Ser345), and cyclin B1 protein levels in prostate cancer cells." (PMID 35651747, 2022). "After topological enrichment, the most connected upregulated genes MYC, CDK1, CCNB1 etc. and the most connected downregulated genes EGFR, VEGFA, STAT3 etc. were categorized according to their highest degree count associated with prostate cancer." (PMID 35456461, 2022). "The results showed that 7 genes were all associated with prostate cancer prognosis, but only UBE2C, TOP2A and CCNB1 were high expression in prostate cancer samples than normal prostate gland samples, the expression of PBK, CDKN3, AURKA, MKI67 were not." (PMID 33630978, 2021). "A study also showed that elevated Cyclin B1 levels served as a biomarker for the prognosis of prostate cancer patients who were being treated with chemotherapy." (PMID 32266115, 2020). "Ellagic acid or ellagitanins from pomegranate juice also inhibited proliferation of prostate cancer cells by inhibiting the expression of cyclin D1 and cyclin B1, and triggered the intrinsic and extrinsic apoptosis pathways." (PMID 31835645, 2019).
prostate carcinoma (continued). "Consistently, Singh and Lokeshwar showed that down regulation of CXCR7 in prostate cancer cells resulted in similar reduced Cyclin B1 and increased p21 expression." (PMID 25168820, 2014). "This is contradicting the results observed in breast and prostate cancer cells where cyclin B1 and Cdc2 expression were inhibited by G-1 stimulation." (PMID 23849542, 2013). "It has been reported that SF induces G2/M arrest by altering the levels of Cyclin B1 in PC-3 and LnCap prostate cancer cell lines." (PMID 23251470, 2012). "Similar observations have been made in prostate cancer cells, thereby providing substantial evidence for a mechanism by which decreased NF-κB signaling in the 8505C cell line leads to decreased cyclin B1 expression in a p21-dependent manner." (PMID 20492683, 2010). "Importantly, recent research has proposed that CCNB1 played a role in the resistance of different cancer types, such as prostate cancer, to chemotherapy." (PMID 40682115, 2025). "In prostate cancer, high expression of cyclin B1 was correlated with tumor aggressiveness." (PMID 40336533, 2025). "Moreover, in human prostate cancer cell lines, cyclin B1 upregulation inhibited cell proliferation and resulted in incomplete cell cycle arrest in the G2/M without entering mitosis." (PMID 37242455, 2023). "Studies demonstrated that α-pinene inhibits cell growth in prostate cancer and ovarian cancer, and induces G2/M cell cycle arrest through up-regulation of Chk1 and Chk2 levels and down-regulation of cyclin B1, CDC25 and CDK1 levels in hepatoma carcinoma BEL-7402 cells." (PMID 34151367, 2021). "Besides, a study in prostate cancer identified CCNB1 as a bona fide AR target gene in prostate stromal cells." (PMID 34797837, 2021). "Similarly, decreased expression of cyclin B1 and increased expression of p21 during G2/M arrest after reversine treatment were also reported in prostate cancer and renal cancer." (PMID 33505802, 2021). "ISL induces cell apoptosis in prostate cancer cells through G2/M cell cycle arrest with concomitant downregulation of cyclin B1, CDK1 (p-Thr14, p-Tyr15, and p-Thr161) (after 48 h of treatment, the IC50 of ISL on PC-3 and 22RV1 is 19.6 and 36.6 μM, respectively)." (PMID 33401375, 2021). "As better risk stratification of patients with prostate cancer is needed, we aimed to investigate whether the expression of BUB3, CCNB1 and PTTG1 could independently predict recurrence after radical prostatectomy." (PMID 31801961, 2020). "Silencing HMGN5 could induce G2/M phase arrest with the downregulation of Cyclin B1 in bladder cancer cells and prostate cancer cells." (PMID 32596388, 2020). "Recent research has shown that Cyclin B1 is involved in breast, prostate cancer." (PMID 32266115, 2020). "Scoring of PTTG1 and CCNB1 may prove challenging due to the low abundance of these proteins in prostate cancer." (PMID 31801961, 2020). "While another study showed that Jagged1 combined with androgen receptor could increase Akt phosphorylation, in turn, phosphorylated Akt further regulated cyclin B1 in prostate cancer cells." (PMID 29636838, 2018). "In this study, cyclin B1 appeared to be the most reactive antigen in prostate cancer and an analysis was performed to determine whether a subset and not necessarily all the 15 TAAs was sufficient to achieve optimal antibody frequency." (PMID 24860838, 2014). "In addition, comprehensive studies on the biology of cyclin B1 in prostate cancer progression and metastatic castration-resistant PCa are guaranteed to better understand the significance of these autoantibodies." (PMID 24860838, 2014). "We also investigate the maximum vital goals in prostate cancer therapy such as AR, prostate specific antigen (PSA), AKT, cyclin B1, cyclin dependent kinase (CDK1), phospho‐androgen receptor (p‐AR), and phospho‐CDK1 (p‐CDK1: T161) expression." (PMID 40336533, 2025).
prostate carcinoma (continued). "In prostate cancer, SLC14A1 downregulation enhances CDK1/CCNB1 and mTOR pathway activity, accelerating tumorigenesis." (PMID 40746552, 2025). "The effects of ISL on prostate cancer cell line DU145 have been investigated, finding that cell cycle arrest in the G2M phase decreases CDC25C and increases p-CDC2 (Tyr15), cyclin B1, and p27KIP1." (PMID 33401375, 2021). "The mitotic checkpoint protein BUB3, cyclin B1 (CCNB1) and pituitary tumor-transforming 1 (PTTG1) regulates cell division, and are sparsely studied in prostate cancer." (PMID 31801961, 2020). "CKS2, TK1, MKI67, TOP2A, CCNB1 and RRM2 directly related to the recurrence and prognosis of prostate cancer." (PMID 32266115, 2020). "To determine our prediction, we found CCNB1, CKS2, MKI67, RRM2, TK1 and TOP2A acted as independent prognostic factors in TCGA prostate cancer." (PMID 32266115, 2020). "The present study is the largest published study on the prognostic value of BUB3, CCNB1, and PTTG1 expression in prostate cancer." (PMID 31801961, 2020). "Overexpression of hPer1 inhibits cell proliferation and reduces the expression of Cyclin B1 and WEE1 proteins, promotes apoptosis, and inhibits cell proliferation in HCT116 human colonic cancer cells and in human prostate cancer cells." (PMID 31130878, 2019). "PKMYT1 promoted the growth of cells by targeting CCNB1 and CCNE1 in prostate cancer." (PMID 36793346, 2022). "The low expression of CCNB1 and PTTG1 observed in this study is in agreement with the low proliferation rates in prostate cancer and comparable to the protein levels found in small-scale studies in prostate cancer." (PMID 31801961, 2020). "On the other hand, similar to our results, PC-3 prostate cancer cells treated with DATS showed no change in cyclin B1 expression." (PMID 28680385, 2017). "Since DATS increased the levels of cyclin B1 protein, we hypothesized that DATS-treated UMSCC-22A and UMSCC-22B cells would be unable to exit the mitosis phase, on the grounds that a similar phenomenon was reported in prostate cancer cells." (PMID 38254868, 2024). "UBE2C, PDZ-binding kinase (PBK), cyclin B1 (CCNB1), Cyclin-dependent kinase inhibitor 3 (CDKN3), topoisomerase II alpha (TOP2A), Aurora kinase A (AURKA) and MKI67 were identified as the candidate hub genes, which were all correlated with prostate cancer patient’ disease-free survival in TCGA." (PMID 33630978, 2021).
ovarian carcinoma (52 papers, 2013 to 2026). A malignant neoplasm originating from the surface ovarian epithelium. "A report using three microarray datasets of ovarian carcinoma showed that ovarian cancer patients with higher CCNB1 expression were associated with poorer overall survival and progression‐free survival." (PMID 41541703, 2026). "In ovarian cancer, the CCNB1 expression was markedly increased and has been linked to enhanced proliferation, migration, and invasion of tumor cells." (PMID 38581717, 2024). "Reported four genes (BUB1B, BUB1, TTK and CCNB1) that were up-regulated DEGs in ovarian cancer associated with poor prognosis using integrated bioinformatical methods." (PMID 39048649, 2024). "CCNB1 was associated with pathologic grade and metastasis of tumors in cases of human breast and ovarian cancer." (PMID 31087508, 2019). "Thus the G-1-induced activation of Cyclin B1 and Cdc2 in ovarian cancer cells is associated with progression in the G2 phase to M phase." (PMID 23849542, 2013). "Specifically, in ovarian carcinoma, CCNB1 overexpression enhanced cell proliferation, migration, and invasion, while its knockdown inhibited these processes." (PMID 40682115, 2025). "CCNA2 is overexpressed in metastatic breast, lung, and bladder cancers, while CCNB1 contributes to metastasis in cervical, breast, and ovarian cancers." (PMID 41244050, 2025). "The forced expression of VASH1 enhanced tubulin carboxypeptidase activity and increased cyclin B1 expression, resulting in augmented paclitaxel chemosensitivity in ovarian cancer cells." (PMID 39710372, 2024). "Western blot analysis of VASH1‐overexpressing ovarian cancer cells revealed upregulated expression of detyrosinated tubulin and cyclin B1 compared with control cells." (PMID 39710372, 2024). "In one previous study, 4 of 16 identified hub genes in the studied sample (CCNB1, CENPF, KIF11, and ZWINT) were associated with decreased OS of patients with ovarian cancer." (PMID 34785763, 2022). "A previous in vitro study showed that overexpression of mortalin (a stress response-related glucose-regulated protein) mediated ovarian cancer cell (A2780) proliferation by inducing abnormal expression of cyclin-B1 and cyclin-D1." (PMID 35334562, 2022). "In the present study, we demonstrated that the knockout of the angiogenesis stimulator, vasohibin‐2 (VASH2) reduced tubulin carboxypeptidase (TCP) activity, increased cyclin B1 expression, and increased paclitaxel chemosensitivity in ovarian cancer cells." (PMID 33710778, 2021). "The gene encoding this protein, ZWINT, was discovered to be overexpressed in ovarian cancer, among other genes (such as CCNB1, CENPF, KIF11) related with cell cycle, nuclear division and oocyte meiosis." (PMID 33445445, 2021). "In ovarian cancer cells, researchers found that the majority of YTHDF1-binding sites in CCNB1 are associated with the m6A sites." (PMID 34359836, 2021). "Meanwhile, CCNB1 has been shown to be over expressed in a variety of tumors, including EOC, and many studies have also demonstrated that cyclin B1 is involved in the differentiation, proliferation, metastasis and chemoresistance of ovarian cancer cell." (PMID 33726773, 2021). "In ovarian cancer cells, the ablation of VASH2 reduced CCP activity and increased cyclin B1 expression results in increased paclitaxel sensitivity in ovarian cancer cells." (PMID 35008169, 2021). "The expression of ITM2A induced G2/M cell cycle arrest and inhibited ovarian cancer cell growth by decreasing the expression of cyclin B1, p-CDC2, CDC2, and CDC25C." (PMID 32300605, 2020). "We previously reported that ISL induced G2/M arrest by up-regulation of CDK2 protein expression and down-regulation of cyclin B1 protein expression in ovarian cancer." (PMID 31394829, 2019). "Cyclin B1, known to interact with and regulate the activity of Cdk1, is mainly expressed in the cytoplasm of ovarian cancer cells." (PMID 27385216, 2016).
ovarian carcinoma (continued). "This was also the first time that EVO increased the expression level of Cyclin B1 in human epithelial ovarian cancer, A2780 and the related PTX-resistant cell lines." (PMID 26553648, 2015). "Previous research also reported that the cell cycle arrest in the G2/M phase via the blockade of cyclin B1/CDC2 in human ovarian cancer cells." (PMID 26138921, 2015). "There was also an up-regulation of Cyclin B1 in ovarian cancer cells, A2780-1A9 that was observed while overcoming multidrug resistance." (PMID 26553648, 2015). "Although Cyclin B1 was always over-expressed and led to uncontrolled growth in many cancer cell lines, when in reference to human ovarian cancer cells, there were a few controversial reports." (PMID 26553648, 2015). "We observed an accumulation of cyclin B1 and Cdc2 regulatory proteins in G-1-treated ovarian cancer cells." (PMID 23849542, 2013). "In this study, the overexpression of VASH1 increased cyclin B1 expression in ovarian cancer cells." (PMID 39710372, 2024). "For instance, four genes (BUB1B, BUB1, TTK, and CCNB1) that are pronouncedly upregulated in ovarian cancer and indicate dismal prognosis were disclosed through bioinformatic methods, and they can be used as potential therapeutic targets for patients with ovarian cancer." (PMID 34434217, 2021). "Moreover, GRP75-overexpression reduced Cyclin-B1 and upregulates Cyclin-D1 and c-myc to promote ovarian cancer cell growth." (PMID 34117210, 2021). "Our results further show the mechanisms underlying the stimulation of proliferation and stemness of ovarian cancer cells by CD83, involving interaction with MAP3K7 and activation of MAPK signaling pathway, as well as downstream FOXO1/p21/CDK2/Cyclin B1 and STAT3/DKK1 cascades." (PMID 32823589, 2020). "We also observed down-regulation of p-Wee1 (Ser642) and Myt1 in Hey and SKOv3ip cells, indicating that the efficacy of Corilagin in inducing G2/M arrest in ovarian cancer cells is possibly due to the down-regulation of cdc2 and Cyclin B1 through Wee1 and Myt1 regulation." (PMID 23410205, 2013). "As the population of EA-treated ovarian carcinoma cells was most in the G1 phase, the cyclin B1 level may be diluted and gradually decreased by increasing the G1 phase cells." (PMID 23843871, 2013). "Furthermore, analyses of cell cycle-related proteins suggest that Corilagin arrested ovarian cancer cells in the G2/M phase by down-regulating the expression levels of Cyclin B1, Myt1, Phospho-Weel (p-Weel) and Phospho-cdc2 (p-cdc2)." (PMID 23410205, 2013). "Besides, cyclin B1 was also highly expressed in the cytoplasm of ovarian cancer cells." (PMID 27385216, 2016). "In conclusion, forced expression of VASH1 in ovarian cancer cells was found to enhance TCP activity, increase cyclin B1 expression, and augment PTX chemosensitivity." (PMID 39710372, 2024). "LncRNA CRNDE not only stimulates ovarian cancer progression by sponging miR-423-5p to upregulate FSCN1 expression, but also activates the miR-183/CCNB1 axis as an oncogene." (PMID 37934582, 2023). "We next measured known FOXM1 downstream targets CCNB1 and CDC25B expression by qPCR in ovarian cancer cells treated with compounds (40 μm; 48 h)." (PMID 35680842, 2022). "The protein expression levels of CCNA2, CCNB1, CDC20, CDCA8, CDK1, KIF11 and TOP2A were high in ovarian cancer tissues, which was further confirmed via the HPA database." (PMID 34253236, 2021). "In conclusion, the knockout of VASH2 reduced TCP activity, increased cyclin B1 expression, and increased PTX chemosensitivity in ovarian cancer cells." (PMID 33710778, 2021). "The knockout of VASH2 reduced TCP activity and increased cyclin B1 expression, resulting in increased PTX chemosensitivity in ovarian cancer cells." (PMID 33710778, 2021). "FOXM1, as a transcription factor, regulated many important proliferation-related target genes (AURB, CCNB1, BIRC5, CDC25, and PLK1, etc.)and was important oncogenic driver in ovarian cancer progression." (PMID 34966670, 2021).